Y_RNA (Y RNA )
Gene: Miscellaneous RNA gene on chromosome 3 (153,607,377 to 153,607,479, forward strand). Ensembl gene ENSG00000200162.
Homologues: Orthologues: chimpanzee Y_RNA (99% identical), macaque Y_RNA (83% identical). Paralogues in human: Y_RNA (85% identical), Y_RNA (84% identical), Y_RNA (83% identical), RNY3 (82% identical), RNY3P2 (82% identical), Y_RNA (82% identical), RNY3P14 (81% identical), Y_RNA (81% identical), Y_RNA (80% identical), RNY3P1 (79% identical), Y_RNA (79% identical), RNY3P16 (78% identical), and 92 more.